MC4R (melanocortin 4 receptor)
Diseases named in the same sentence as MC4R in open-access papers (continued):
Sharing a sentence is not in itself a finding about the gene and the disease.
Obesity (continued). "In 2008, the melanocortin 4 receptor (MC4R) gene was reported as the second association signal for common obesity by the GWAS." (PMID 23049848, 2012). "Characterization of MC4R mutations in in vitro cell systems has resulted in the identification of different mechanisms by which obesity-linked MC4R variants can cause defective function." (PMID 23251400, 2012). "The rs17782313 polymorphism near the MC4R gene was found to be associated with obesity among both European adults [odds ratio (OR) = 1.12, 95% confidence interval (CI) = 1.08–1.16, p = 5.2×10−9)] and children (OR = 1.30, 95%CI: 1.20–1.41, p = 8.0×10−11)." (PMID 23049848, 2012). "A few studies have also jointly analyzed the FTO and MC4R polymorphisms, describing their additive effects on obesity related variables." (PMID 23284998, 2012). "Fat mass and obesity (FTO) and melanocortin-4 receptor (MC4R) and are relevant genes associated with obesity." (PMID 23284998, 2012). "This has led to the identification of different forms of monogenic obesity, with mutations in the melanocortin-4 receptor (MC4R) gene, a single exon gene on 18q22, being the most frequent." (PMID 23251400, 2012). "This ratio was decreased by approximately 3-fold for the obesity-associated HA-MC4R-GFP P272L mutant as compared to wt, indicating intracellular retention similar to other obesity-associated MC4R mutants that are misfolded in the ER." (PMID 23251400, 2012). "Although previous studies have reported several rare MC4R mutations in the development of extreme and early-onset obesity, recent publications have identified several common genetic polymorphisms near the MC4R gene contributing to the common obesity." (PMID 23049848, 2012). "Heterozygous mutations in the melanocortin-4 receptor (MC4R) gene represent the most frequent cause of monogenic obesity in humans." (PMID 23251400, 2012). "Another polymorphism (rs12970134) near the MC4R gene was also suggested to increase the risk of obesity among Europeans (OR = 1.12, 95%CI 1.06–1.17, p = 9.9×10−16)." (PMID 23049848, 2012). "Mutation of the melanocortin-receptor 4 (MC4R) is the most frequent cause of severe obesity in humans." (PMID 22479599, 2012). "Mutations in the MC4R gene can decrease this response and lead to rare familial forms of severe obesity." (PMID 22701495, 2012). "We retrieved all published literature that investigated association of MC4R variants with obesity from PubMed and Embase." (PMID 23049848, 2012). "We have previously shown that cell exposure to a chemical chaperone, PBA, increases plasma membrane expression of wt-MC4R and of some obesity-associated MC4R variants that are retained in the ER." (PMID 23251400, 2012). "This large meta-analysis confirmed the significant association of rs17782313 polymorphism near the MC4R gene with susceptibility to common obesity." (PMID 23049848, 2012). "The risk variant has subsequently been associated with higher energy and fat intake and the increased BMI reported in children, is consistent with early onset obesity caused by MC4R mutations." (PMID 21466928, 2011). "Several independent genome-wide association studies recently identified two common polymorphisms, FTO rs9939609 and MC4R rs17782313, that are linked to increased body weight and obesity." (PMID 21347432, 2011). "Three reported susceptibility loci for obesity harbour genes that are known to be involved in catabolic hypothalamic pathways (MC4R, PCSK1, and BDNF) and many others contain genes that are highly expressed in the central nervous system." (PMID 21708048, 2011). "Through the first collaboration in obesity research, a strong association was detected between SNPs located 188 kilobases (kb) downstream from the melanocortin 4 receptor gene (MC4R) and BMI." (PMID 21466928, 2011). "Other genes have also been associated with obesity in the general population, most notably the melanocortin-4-receptor (MC4R) and the fat mass and obesity-associated (FTO) genes." (PMID 21298202, 2011).
Obesity (continued). "The MC4R gene is the second gene found by GWAS to be associated with BMI, and, while only marginally associated with obesity in our study, its odds ratio was 1.3." (PMID 21552555, 2011). "Heterozygosity for deleterious coding mutations in MC4R or POMC has been associated with a non fully penetrant form of obesity, whereas partial LEP or LEPR deficiency has been associated with a higher percentage of body fat mass." (PMID 22043164, 2011). "Larger GWA meta-analysis, through the Genetic Investigation of Anthropometric Trait (GIANT) Consortia and deCODE followed reporting 8 novel obesity loci, as well as confirming the MC4R and FTO associations." (PMID 21466928, 2011). "Carriage of the FTO rs9939609 A and MC4R rs17782313 C alleles was estimated to increase the risk of obesity by 31% and 12%, respectively." (PMID 21347432, 2011). "For instance, common polymorphisms in the melanocortin-4 receptor gene (MC4R) have been associated with human obesity in two candidate gene meta-analyses." (PMID 21390334, 2011). "An age-dependent penetrance of MC4R pathogenic and monogenic mutations on obesity has been found in multigenerational pedigrees, the effect of mutations on the obesity phenotype being amplified by the development of an "obesogenic" environment." (PMID 22043165, 2011). "QTDT analysis further revealed that five SNPs in FTO and two in MC4R were significantly associated with obesity in the PCOS families." (PMID 21283731, 2011). "Two gain-of-function infrequent coding polymorphisms (I251L and V103I) in MC4R have been negatively associated with obesity." (PMID 22043164, 2011). "With the development of high-throughput genotyping techniques and the implementation of genome-wide association studies (GWAS), common variations, such as those in FTO and MC4R, have been associated with obesity and body mass index (BMI)." (PMID 21552555, 2011). "Together, these MC4R gene variants have not only been associated with promoting and protecting from obesity, but also with traits related to the intake and preference for foods." (PMID 22043166, 2011). "Recent two genome-wide association studies revealed that common allelic variants in MC4R locus are associated with obesity-related phenotypes." (PMID 19822564, 2011). "The 18q region, which has been linked to several physical activity phenotypes, flanks a candidate gene, MC4R, whose mutations have been associated with the development of obesity." (PMID 22126647, 2011). "Genetic ablation of melanocortin 4 receptor gene in mice produces hyperphagia and obesity while rare mutations in the corresponding human MC4R are a cause of severe childhood obesity." (PMID 21695122, 2011). "The association of the two major contributors to polygenic obesity (SNP rs17782313 near MC4R and SNP rs1421085 / rs9939609 in FTO) with food intake / food behavior-related endophenotypes has been well documented in the literature." (PMID 22043165, 2011). "The activation of MC4R causes anorexia whereas inactivation of the MC4R leads to overeating and obesity." (PMID 21850219, 2011). "Alleles of common single nucleotide polymorphisms (SNPs) rs12970134 and rs17782313 located downstream of the MC4R (154 kb and 188 kb, respectively) were shown to be associated with obesity and related traits." (PMID 21085626, 2010). "The respective SNP was associated with obesity; it is located 188 downstream of the MC4R; its effect is presumably exerted by an influence on the expression of the gene." (PMID 20092643, 2010). "Since mutations in the human MC4-R or deletion in mouse models have been associated with obesity, this receptor has received much attention as a potential drug target to treat this pathology." (PMID 20976162, 2010). "Phenotypical effects of MC4R mutations other than obesity have been shown to encompass hyperinsulinemia, elevated growth rates and higher bone density." (PMID 21085626, 2010).
Obesity (continued). "On the other hand, approximately 130 mutations have been detected in the human MC4R gene; those leading to a reduced function result in a dominantly inherited form of obesity." (PMID 21085626, 2010). "In sum, we detected a haplotype covering the MC4R coding region; or at least a secondary independent signal 5′ of the MC4R which is associated with extreme obesity." (PMID 21085626, 2010). "Recently, two GWASs established that a common genetic variant near MC4R gene (rs17782313) was associated with increased obesity risk and insulin resistance." (PMID 20161779, 2010). "It is unclear if the SNPs directly influence MC4R function or expression, or if the SNPs are on a haplotype that predisposes to obesity or includes functionally relevant genetic variation (synthetic association)." (PMID 21085626, 2010). "At the MC4R locus, common SNPs are associated with polygenic forms of obesity and variants leading to a reduced MC4R function entail a major gene effect for obesity." (PMID 21085626, 2010). "Conditional logistic regression analysis including effects of the two-marker haplotype SNPs (rs12970134, rs1943229), the two coding polymorphisms (weight lowering effect: Val103Ile, Ile251Leu) and any other functionally relevant obesity MC4R mutations." (PMID 21085626, 2010). "A haplotype reaching from a region 5′ of the MC4R to a region at least 150 kb from the 3′ end of the gene showed a stronger association to obesity than single SNPs." (PMID 21085626, 2010). "Recent genome wide association scans have identified regions in the FTO gene and variants telomeric to the MC4R gene to be associated with obesity." (PMID 19183461, 2009). "We have previously reported suppression of obesity, hyperinsulinemia and hyperglycemia in Ay/a agouti and melanocortin 4 receptor deficient (MC4R-/MC4R-) mice by targeted deletion of the Vgf gene." (PMID 19863797, 2009). "Children carrying MC4R mutations seem to show a particular phenotype characterized by early onset, severe obesity and high stature." (PMID 19284607, 2009). "In this study, we examined the ovarian morphology of obese mice with an ENU-induced obesity-causing mutation (I194F) in MC4R." (PMID 19309531, 2009). "Common variants in the FTO gene and near the MC4R gene are associated with modest, yet consistent effects on BMI (0.2-0.4 kg/m2 per allele) that translate into odds ratio of 1.1-1.3 for obesity." (PMID 20017980, 2009). "Dysfunction of the MC4R appears to be a relatively common factor in early onset obesity and more than 80 different obesity-associated MC4R mutations have been identified so far." (PMID 19309531, 2009). "Melanocortin-4-receptor (MC4R) mutations represent the most frequent genetic cause of non-syndromic early onset obesity." (PMID 19284607, 2009). "Recent genome-wide association studies have identified two genes (FTO and near MC4R) that were unequivocally associated with body mass index (BMI) and obesity." (PMID 20017980, 2009). "MC4R mutations represent the most frequent cause of non syndromic early onset obesity, with prevalence ranging from 0.5% to 5%." (PMID 19284607, 2009). "Other well-replicated obesity loci, including MC4R, have also been shown to be associated with centrally-mediated phenomena including binge eating behavior." (PMID 19557197, 2009). "Defects in the genes for leptin, leptin receptor, proconvertase 1, pro-opiomelanocortin (POMC) and the melanocortin receptors MC3R and MC4R have been associated with obesity." (PMID 19309531, 2009). "Molecular screenings allowed to identify mutations on POMC and MC4R associated with early onset obesity." (PMID 19284607, 2009). "Reduced penetrance and variable expressivity of obesity has been found to be associated with MC4R mutations." (PMID 19284607, 2009). "The melanocortin-4 receptor (MC4R) gene, located on chromosome 18q21.32, is the second obesity-susceptibility gene discovered by genome-wide association studies in individuals of European origin." (PMID 19461885, 2009).
Obesity (continued). "Mutations in melanocortin-4 receptor have been observed more than any other monogenic obesity disease at 1–6% of the surveyed obese population." (PMID 18752667, 2008). "The Ile103 allele of the Val103Ile polymorphism of the MC4R gene has repeatedly been reported in several studies with a large number of cases and controls to be negatively associated with obesity and increased BMI." (PMID 18377640, 2008). "The observation that loss-of-function mutations in MC4R are often correlated with early-onset obesity suggests that MC4R plays a role during neonatal life, however its selective role in adulthood can be evaluated in MC4-RASSL knock-in transgenic mice." (PMID 17668051, 2007). "sim1 heterozygous deficient mice have a similar phenotype to MC4R deficient and lethal yellow mice, with obesity resistant to the effects of melanocortins." (PMID 17764572, 2007). "Haploinsufficiency of Sim1 is associated with hyperphagic obesity and increased linear growth closely resembling the phenotype of agouti yellow (Ay), and Mc4r null mice, two classic models of disrupted hypothalamic melanocortin signaling." (PMID 17448988, 2007). "The loss of α-MSH-mediated activation in the human MC4R mutations is thought to be the basis of the obesity in patients carrying these mutations." (PMID 17668051, 2007). "For example, loss of basal activity of MC4R is associated with human obesity, and increased basal Gs signaling has been associated with increased cell proliferation and tumor formation in the pituitary and other endocrine glands." (PMID 17668051, 2007). "A frequent autosomal-dominant form of obesity stemming from mutations in MC4R was simultaneously reported by two groups, first in family studies and then in case-control studies." (PMID 17196040, 2006). "Recent evidence has demonstrated that the infrequent V103I polymorphism in MC4R is negatively associated with serum triglyceride levels, body mass index, and obesity." (PMID 17196040, 2006). "Since these initial reports, MC4R-linked obesity remains the most prevalent form of monogenic obesity identified to date, representing approximately 2%–3% of childhood and adult obesity." (PMID 17196040, 2006). "Early, targeted efforts focusing on diet and physical activity may help reduce long-term obesity and complication risk in MC4R variant carriers, but evidence is limited." (PMID 41489710, 2026). "A study of 31 adults with obesity due to MC4R deficiency indicated that tirzepatide, a dual GLP-1 and glucose-dependent insulinotropic polypeptide (GIP) receptor agonist, may be a particularly effective therapeutic strategy." (PMID 41489710, 2026). "Hence, loss of function or haploinsufficiency of the SIM1 protein results in a reduction in the MC4R neuronal populations in the paraventricular nuclei, contributing to hyperphagia and obesity, similar to the MC4R deficiency." (PMID 41516406, 2026). "Genetic factors implicated in treatment variability include variants in GLP-1 receptor, GIP receptor, β-arrestin 1, transcription factor 7-like 2, fat mass and obesity-associated protein, and melanocortin 4 receptor, although tirzepatide-specific validation remains limited." (PMID 42198465, 2026). "In fact, inactivating mutations in the MC4R gene are the most common form of monogenic obesity." (PMID 42012887, 2026). "We investigate whether obesity-associated variants of MRAP2 alter their ability to modulate MC4R and GHSR signalling as a possible mechanistic link to the development of obesity." (PMID 41758604, 2026). "Genetic polymorphisms in MC4R can affect receptor function and disrupt the normal regulation of appetite, leading to dysregulated eating behaviors and an increased risk of overeating and obesity." (PMID 41002740, 2025). "Among other effects, GNAS variants may impair signaling of MC4R, a G‐protein–coupled receptor, leading to hyperphagia and early‐onset obesity." (PMID 40528426, 2025).
Obesity (continued). "Similarly, mutations in the melanocortin 4 receptor (MC4R) gene are linked to early-onset obesity, underscoring its role in energy balance and weight regulation." (PMID 40428329, 2025). "Recent evidence suggests that obesity-related changes in the brain, including alterations in melanocortin signaling via the melanocortin-4 receptor (MC4R), may underly altered chemosensitivity." (PMID 39542230, 2025). "This may reflect our inclusion of BMI as a covariate to identify variants with BMI-independent effects, and gain-of-function variants in MC4R are known to have BMI-independent protective effects against obesity and type 2 diabetes." (PMID 40065360, 2025). "Although clinical presentations may vary among these MC4R pathway diseases, hyperphagia associated with obesity is the most consistent characteristic." (PMID 40528426, 2025). "As deficiency in MRAP2 partly affects the MC4R pathway, the subsequent energy homeostasis dysregulation and obesity in MRAP2-deficient subjects might be theoretically improved by an MC4R-agonist treatment." (PMID 40822950, 2025). "However, some variants did not affect cAMP signaling which is consistent with previous studies of obesity-associated MC4R mutations." (PMID 39807633, 2025). "High-quality studies as well as further study on the mechanisms involved are needed to assess whether an imbalance in macronutrient intake could also explain why MC4R rs17782313 is associated with obesity." (PMID 38879444, 2025). "Enrichment of MC4R in cilia requires its interaction partner, the single pass membrane protein melanocortin receptor accessory protein 2 (MRAP2) and deletion of MRAP2 or mutations that block ciliary targeting of MC4R result in profound obesity in human patients and in mice." (PMID 39899600, 2025). "The literature has reported the weight loss effects of GLP-1-based therapies for individuals with obesity due to MC4R pathway mutations, and GLP-1 agonists might be an effective option in managing hypothalamic obesity." (PMID 40104296, 2025). "In Chandigarh, India, next-generation sequencing in children with obesity identified one pathogenic variant in the MC4R gene, one likely pathogenic variant each in the LEPR, NTRK2, and LEP genes, as well as variants of uncertain significance in the POMC and LEPR genes." (PMID 40149731, 2025). "However, MC4R-related obesity was often associated with linear growth; fasting hyperinsulinemia; an increased risk of hypertension; reduced energy expenditure; and increases in lean mass, fat mass, and visceral fat." (PMID 40001512, 2025). "While monogenic nonsyndromic obesity (such as mutations in the MC4R, LEP, or POMC genes) generally presents with severe hyperphagia and weight gain in early life but otherwise normal neurocognitive development, syndromic forms typically display additional systemic or neurological features." (PMID 40689079, 2025). "Although rare monogenic obesity syndromes (e.g., those caused by mutations in the LEP gene, leptin receptor gene (LEPR), melacortin 4 receptor (MC4R), and fat mass and obesity-associated gene (FTO)) provide valuable information about the pathways regulating body weight." (PMID 41150735, 2025). "Critically, challenges with weight management increase the risk and severity of obesity, obesity-related comorbidities, and premature death, which may be further heightened in patients with rare MC4R pathway diseases." (PMID 40560452, 2025). "In addition, several studies showed the association of the MC4R gene and its role in energy balance, food intake regulation, total fat, total obesity, peripheral obesity, abdominal obesity, and higher BMI87,88." (PMID 40628909, 2025). "Severe Obesity, severe hyperinsulinemia, increased lean body mass, and linear growth of the five known melanocortin receptors are clinical characteristics of mutant carriers; MC4R has been most closely associated with regulating energy balance in rats." (PMID 41302083, 2025).